VWF (von Willebrand factor)
Diseases named in the same sentence as VWF in open-access papers (continued):
Sharing a sentence is not in itself a finding about the gene and the disease.
breast cancer (42 papers, 2002 to 2026). A primary or metastatic malignant neoplasm involving the breast. "Multiple studies have demonstrated that elevated plasma levels of VWF are linked to a poorer prognosis in patients with liver cancer, breast cancer, and NSCLC." (PMID 37953280, 2023). "Furthermore, a lower pre-treatment vWF concentration is a predictor of a high risk of breast cancer recurrence." (PMID 37626742, 2023). "Intriguingly, VWF levels fell in the fifth week following inoculation of breast cancer cell in mice, however the underlying biological mechanism mediating this decrease remains unclear." (PMID 33571850, 2021). "In breast cancer specifically, an association has been found between an increase in VWF concentration and a higher tumour grade, and that VWF could potentially be a biomarker of relapse." (PMID 33571850, 2021). "Still, in our hands, a rise in plasma vWF concentration was noted rather late, suggesting that vWF may be implicated during the late phase of murine breast cancer metastasis." (PMID 30683749, 2019). "Importantly, the mechanisms by which VWF may mediate metastasis in breast cancer are beginning to be elucidated, as implicated by several studies." (PMID 33571850, 2021). "A recent study showed that the overexpression of VWF in breast cancer cells leads to an increase in VEGF-A-related angiogenesis." (PMID 40699668, 2025). "Breast cancer expressed GPIb together with VWF contributed to tumor cell aggregation, tumor cell spreading and filopodia formation on VWF, and finally enhanced cancer cell transmigration." (PMID 35366951, 2022). "A specific HDAC inhibitor, MS-275, has been shown to significantly reduce tumor growth, decrease VWF-positive blood vessels, decrease lung metastasis and reverse epithelial-mesenchymal transition in an in vivo murine model of breast cancer." (PMID 35327035, 2022). "For the first time, this review systematically and specifically reports on the accumulating evidence for the biological role of VWF in breast cancer including interaction with breast tumour cells, apoptosis, angiogenesis and breast cancer metastasis." (PMID 33571850, 2021). "With regards to VWF expression in different subtypes of breast cancer, it has been reported that patients with invasive lobular carcinoma (ILC) have higher VWF RNA expression than patients with invasive ductal carcinoma (IDC) and other histology presentations." (PMID 33571850, 2021). "It has been reported that breast cancer cells exert a significant effect on the upregulation of angiogenic genes, including VWF, thus promoting metastasis." (PMID 33571850, 2021). "For example, in breast cancer, plasma VWF levels are significantly elevated in patients with malignant disease compared to benign conditions and healthy controls." (PMID 33571850, 2021). "The adhesion of circulating VWF to tumour cells via αvβ3 integrin, mediates apoptosis of several tumour cell lines in vitro, including breast cancer cells MCF-7." (PMID 33571850, 2021). "In this review, we provide an overview of VWF in orchestrating the pathological process of breast cancer dissemination, and provide supporting evidence of the role of VWF in mediating metastatic breast cancer." (PMID 33571850, 2021). "In conclusion, we found that a 12-month physical activity intervention significantly increased FVIIAg levels and inhibited an increase in VWF among postmenopausal breast cancer patients." (PMID 33564742, 2021). "In breast cancer, a significant rise in the plasma levels of VWF has been reported in patients with malignant disease compared to benign conditions and healthy controls, with an even greater increase seen in patients with disseminated disease." (PMID 33571850, 2021). "These conflicting opinions also highlight the need for further research in the area in order to fully define the role of VWF in breast cancer metastasis." (PMID 33571850, 2021).
breast cancer (continued). "In contrast, 5 weeks after 4T1 breast cancer cell inoculation, the capacity of platelets to bind fibrinogen and vWF was significantly diminished in basal conditions as well as after ADP stimulation." (PMID 30075800, 2018). "The patient safely underwent curative surgery for her breast cancer with supplementation of FVIII/VWF concentrates." (PMID 30225530, 2018). "Double immunohistochemical staining for CCL18 and CD34/CD31/vWF was performed in 80 breast cancer samples to study the correlation between CCL18+ TAMs and microvascular density (MVD)." (PMID 26416449, 2015). "Tumor neovascularization was assessed by quantification of MVD in mammary tumors by vWF immunohistochemistry." (PMID 24416386, 2014). "The expression pattern of CD45, CD34, CD31 and VWF in both cervical and breast cancer was highly variable between individuals being examined." (PMID 18286204, 2008). "To further confirm that TVECs were defective in phenotype and function, we examined expression of CD45, CD34, CD31 and VWF in the native human cervical and breast cancers." (PMID 18286204, 2008). "We also quantified the levels of VE-cadherin, PECAM-1 and vWF as an indicator of degree of angiogenesis in breast cancer, as we previously reported." (PMID 16430777, 2006). "Disseminated breast cancer cells residing in bone marrow perivascular niche are protected from chemotherapy by their integrin-mediated interactions with molecules including von Willebrand Factor (VWF) and vascular cell adhesion molecule-1 (VCAM-1)." (PMID 35994202, 2022). "We analyzed MVD through CD34 and vWF, and we found that CD34 and vWF had obvious correlation in breast cancer tissues, which meant that these two indicators could reflect MVD in breast cancer." (PMID 36465358, 2022). "Moreover, a recent study demonstrates how the overexpression of VWF in breast cancer cells upregulates VEGF-A-related angiogenesis." (PMID 35327035, 2022). "Another study has shown that VWF tumour mRNA levels correlated with its VWF serum protein levels in patients with HER2-negative breast cancer, suggesting that VWF might be produced by tumour cells with an outflow to the systemic circulation." (PMID 33571850, 2021). "However, in this case, adhesion of VWF via the αvβ3 integrin induces apoptosis in breast cancer cells." (PMID 33571850, 2021). "Their data further suggested that VWF is also relevant for the growth of micrometastases as anti-VWF treatment resulted in a reduced count of brain metastases and a smaller mean macrometastasis size in both melanoma and breast cancer models." (PMID 34572000, 2021). "In a study using a 4T1 murine model of breast cancer metastasis, plasma levels of VWF have been found to be significantly elevated at the late phases of metastasis, specifically in the fourth to fifth week after cancer cell inoculation, when robust metastatic lesions had formed in the lungs." (PMID 33571850, 2021). "Additionally, tumor cell survival in the perivascular niche was reduced in the breast cancer model in the presence of anti-VWF antibodies." (PMID 34572000, 2021). "Taken together, this highlights several distinct mechanisms through which VWF may interact with breast cancer cells, by direct adhesion via a number of integrins or indirectly through platelet-VWF interactions." (PMID 33571850, 2021). "Von Willebrand factor C and EGF domain (VWCE) is a member of the Von Willebrand factor (VWF) gene family; however, its function, regulatory mechanism, and clinical value in breast cancer remain unclear." (PMID 33194737, 2020). "Therefore, we decided to perioperatively supplement with plasma-derived factor VIII (FVIII) containing von Willebrand factor (FVIII/VWF concentrates) to perform curative surgery for breast cancer safely." (PMID 30225530, 2018). "Finally, TVECs in human native cancers such as cervical and breast cancers were found to be defective in phenotype and function (VWF expression)." (PMID 18286204, 2008).
breast cancer (continued). "Given the relationship between HDAC and VWF gene expression, and the previously discussed mechanisms by which the VWF may promote tumor metastasis, it is possible that the effect of HDAC inhibitors in attenuating breast cancer metastasis may include the targeting of VWF expression." (PMID 35327035, 2022). "Consistent with the association of high VWF expression and shortened MCL survival, high expression of VWF may promote metastatic dissemination of the MCL tumor cells, as it was reported to promote metastasis in gastric adenocarcinoma and breast cancer." (PMID 36359790, 2022). "In addition, these data suggest that transcriptional targeting of VWF expression via HDAC inhibitors may serve to attenuate breast cancer metastasis." (PMID 33571850, 2021). "Consequently, understanding the role of VWF in the setting of breast cancer may not only serve to attenuate metastasis but also reduce the risk of thrombosis." (PMID 33571850, 2021). "Additionally, expression of GPIbα on the surface of breast cancer cells was shown to promote tumor cell spreading through cytoskeleton rearrangement and tumor migration in vitro when exposed to a surface coated with human VWF." (PMID 34572000, 2021). "For a patient with aVWS, which carries a high risk of hemorrhage during the perioperative period, initiation of appropriate management like supplementation of FVIII/VWF concentrates might enable safe curative surgery for breast cancer, and collaboration with the hematology department is critical." (PMID 30225530, 2018). "To our knowledge, to date, there have been no reports on perioperative management for breast cancer patients with VWF; thus, we believe that our report may provide useful information for clinicians involved in breast cancer treatments or other invasive procedures." (PMID 30225530, 2018). "Von Willebrand Factor (vWF), a pro-angiogenic factor, promotes angiogenesis by triggering VEGF-A via PI3K/Akt/miR-205-5p pathway in breast cancer cells." (PMID 39858015, 2025). "The role of VWF, PRG4, and PPBP on breast cancer is predicted to be on tumor progression and metastasis." (PMID 37268731, 2023). "We next planned to study the role of EndMT in angiogenesis of breast cancer, then we performed double-IHC staining for EndMT markers (α-SMA, FSP-1, Vimentin, VE-Cadherin and Fibronectin), and MVD (CD34, vWF) on IDC samples." (PMID 36465358, 2022). "To investigate the potential role of neovascularization in breast cancer, we first performed IHC staining for MVD (CD34, vWF), an important quantitation of the neovascularization, on samples from 86 IDC patients." (PMID 36465358, 2022). "In the bone perivascular niche, α5β3 and α4β1 integrins are stimulated by von Willebrand Factor (VWF) and VCAM-1, respectively, from the endothelial cells and actively sustain chemoresistance of bone-disseminated breast cancer cells." (PMID 31963820, 2020). "In mouse models of breast cancer and colon cancer, MSCs promoted tumor angiogenesis but did not differentiate into cluster of differentiation 31 (CD31) or von Willebrand factor (vWF)-positive endothelial cells." (PMID 24502410, 2014). "Using this methodology, we identified nine proteins—FN1, VWF, PRG4, MMP9, CLU, PRDX6, PPBP (CXCL7), APOC1, and CHL1—that were robustly quantified in serum and showed statistically significant differences between breast cancer patients and healthy controls." (PMID 40940928, 2025). "The aggressive MDA-MB-231 breast cancer cells have been shown to express higher levels of ADAM28 and demonstrate resistance to VWF-induced apoptosis, whereas the less aggressive MCF7 breast cancer cells have been found to express lower levels of ADAM28 and are susceptible to apoptosis." (PMID 33571850, 2021).
breast cancer (continued). "An in vivo study of breast carcinoma in a murine model treated with the HDAC inhibitor MS-275 demonstrated significantly reduced tumour growth, decreased VWF-positive blood vessels (decreased angiogenesis), decreased lung metastasis and reversed epithelial-mesenchymal transition (EMT)." (PMID 33571850, 2021). "Median expression of P-selectin, active form GPIIb/IIIa, vWF, and bound fibrinogen on the unstimulated platelet surface was not altered in 4T1 breast cancer-bearing mice as compared with controls." (PMID 30075800, 2018). "Based on previous studies that have shown a protective role of VWF in the initiation of metastatic foci, a phase II dose-escalation clinical trial (NCT01606072) investigated the provision of high-dose perioperative desmopressin (dDAVP) to reduce metastasis in breast cancer patients." (PMID 33571850, 2021). "However, after ADP stimulation, platelet surface expression of vWF and fibrinogen but not P-selectin and active form of GPIIb/IIIa was increased to a lesser extent in 4T1 breast cancer-bearing mice as compared with healthy controls." (PMID 30075800, 2018). "Moreover, MCF-7 breast cancer cells have been reported to express pseudo-GPIbα receptors on their surface which may facilitate direct interactions with VWF, independent of platelets." (PMID 33571850, 2021). "The increase in central necrosis in mammary tumors may allude to antiangiogenic and/or cytotoxic actions of TNJ treatment; however, the lack of a difference in von Willebrand factor immunostaining between control and TNJ-treated tumors does not support this potential mechanism." (PMID 22619689, 2012).
Obesity (41 papers, 2007 to 2026). Accumulation of substantial excess body fat. "The obtained results indicate a potential mechanism of obesity-induced thrombotic complication caused by fatty acid activation of NF-κB signalling and vWF upregulation and help to identify various compensatory mechanisms related to TLR4 signal transduction." (PMID 38203423, 2023). "Obesity stimulates chronic inflammation, which may increase the levels of coagulation factors in plasma, such as fibrinogen, von Willebrand factor, and factor VIII, further increasing the risk for thrombotic events." (PMID 40568021, 2025). "Furthermore, obesity is associated with elevations in coagulation and von Willebrand factor as well as impaired fibrinolysis." (PMID 39395119, 2024). "Obesity is associated with inactivity, raised intra-abdominal pressure, a chronic low-grade inflammatory state, impaired fibrinolysis, high levels of fibrinogen, von Willebrand factor, and factor VIII, leading to a prothrombotic condition and elevated risk of VTE." (PMID 41035602, 2025). "Older age, obesity, and impaired renal function are associated with a prothrombotic state, and this is why statistical analysis was corrected for these variables showing that D-dimer, F1 + 2, and vWF were all independently related to both AUC-cortisol and DST-cortisol." (PMID 38836224, 2024). "This argues against a major confounding of vWF by inflammation and obesity and suggests that vWF alone is the major contributor of the coagulation system to cluster-specific mortality risk." (PMID 39175055, 2024). "It is worth noting that individuals in the family under study with reduced levels of miR-143/145 and high (II-9)/extremely high (II-3, II-8) levels of VWF suffer from a different type of obesity." (PMID 37762470, 2023). "After adjustment for age, obesity and smoking, VTE risk was associated with coagulation factor VIII, factor IX, von Willebrand factor (VWF), activated partial thromboplastin time (APTT), and fibrin D‐dimer." (PMID 35655415, 2022). "Circulating concentrations of the inflammatory markers fibrinogen (P<0.001), homocysteine (P=0.037), CRP (P=0.033) and vWF (P=0.029) were increased in patients with obesity." (PMID 35222417, 2022). "Levels of VWF are increased in obesity and they result from both an increased synthesis and impaired clearance rather than from shedding which explains an unaltered formation of KC-platelet aggregates." (PMID 33673387, 2021). "Adherence to the ‘high-fat/low-fibre’ dietary pattern showed a strong positive associationwith current smoking, heavy drinking, physical inactivity, manual social class, obesity,total energy intake, CRP and vWF and an inverse association with HDL." (PMID 27620002, 2016). "In subjects with obesity, there was a significantly greater decrease in tissue plasminogen activator (t-PA) antigen and vWF in the metformin than in the placebo group." (PMID 25510597, 2014). "Obesity is associated with several factors like raised intra-abdominal pressure, immobility, chronic impairment of fibrinolysis, high levels of fibrinogen, factor VIII levels, von Willebrand factor, and a low-grade inflammatory state." (PMID 38586707, 2024). "In detail, studies revealed that early AFB (younger than 20 years) was associated with several cardiovascular factors by mid-life, including body mass index, obesity, blood pressure, cholesterol, triglycerides, glycated haemoglobin, C reactive protein, von Willebrand factor, and fibrinogen." (PMID 37024926, 2023). "Obesity is associated with increased levels of several components of the coagulation cascade including tissue factor (TF), factors VII and VIII, von Willebrand factor (vWF), plasminogen activator inhibitor-1 (PAI-1), factor XIII B subunit and fibrinogen." (PMID 22920475, 2012).
Obesity (continued). "Available evidence suggests that although MBS reduces obesity-related inflammation and oxidative burden in many patients, a proportion of individuals may present with persistent redox imbalance, elevated D-dimer or vWF (von Willebrand Factor), and delayed normalization of fibrinolysis." (PMID 41596182, 2026). "Levels of fibrinogen, von Willebrand factor (vWF), and factors VII and VIII are also increased in patients living with obesity." (PMID 39269539, 2025). "Obesity as well as the analyzed components of the MetS did not affect VWF levels in univariate analyses, and thus, were not included in multivariate models." (PMID 32052552, 2020). "Among the target genes with the highest absolute CAP score difference are VWF (which is targeted by antihemophilic factor), SIRT5 (targeted by suramin for treating sleeping sickness), and the gastric lipase LIPF (targeted by orlistat for obesity treatment)." (PMID 29273096, 2017). "Moreover, patients with obesity exhibited increased circulating levels of markers of systemic inflammation, including C-reactive protein (CRP), fibrinogen, von Willebrand factor, or TNF-α (all p < 0.05), regardless of insulin resistance." (PMID 32512939, 2020). "The correlations found between VAT, PAT, and vWF may reflect increased inflammatory or pro-thrombotic activity in these adipose tissues whereas SAT and general obesity assessed by BMI did not display a similar correlation." (PMID 28570705, 2017). "Thus, in the nutritional obesity model, our results revealed an increase in transaminases, bilirubin, damage score, ALP, von Willebrand Factor and hyaluronic acid levels in both steatotic and non-steatotic grafts of the BD + LT group when compared with the results of the LT group." (PMID 34444713, 2021).